SIRT1 (sirtuin 1)
Diseases named in the same sentence as SIRT1 in open-access papers (continued):
Sharing a sentence is not in itself a finding about the gene and the disease.
cardiomyopathy (continued). "In general, the ability of SIRT1 to inhibit p38 MAPK/NF-κB pathways reduces the levels of other inflammatory cytokines in DOX-induced cardiomyopathy, such as IL-1β, IL-6, IL-17, and TNF-α." (PMID 36408244, 2022). "Doxorubicin cardiomyopathy is antagonized by acacetin treatment through Sirt1-mediated activation of AMPK/nuclear factor E2-related factor 2 (Nrf2) signaling." (PMID 36299901, 2022). "Thus, the regulatory impact of HOTAIR on SIRT1 seems to be complex and likely context- and/or cell-type-dependent, as illustrated by its potential for SIRT1 upregulation via sponging miRNA34a, which is associated with cardio-protective effects in a murine cardiomyopathy model." (PMID 34685689, 2021). "In conclusion, fisetin exerts its therapeutic effects against DOX-induced cardiomyopathy by inhibiting ferroptosis via SIRT1/Nrf2 signaling pathway activation." (PMID 35273493, 2021). "Considering that cardiomyopathy is the main cause of death in DMD, different studies elucidated the role of SIRT1 activators in ameliorating cardiac function of dystrophic hearts." (PMID 34205021, 2021). "Recently, Wei WY and colleagues reported that CTRP3 prevents sepsis-induced cardiomyopathy in mice by activating AMPKα signaling and ameliorates doxorubicin-induced cardiomyopathy via activating Sirt1." (PMID 33343381, 2020). "A plausible mechanism accounting for miR-22-mediated GOF cardiomyopathy came from our observation that vital cardiac genes SIRT1, PGC-1α, and PPARα are co-repressed by miR-22 in the heart." (PMID 24086656, 2013). "In summary, we found that administration of the small-molecule compound JQ-1 improved cardiac remodeling after MI by inhibiting ferroptosis through the NAMPT/SIRT1 pathway, indicating a novel potential strategy for the intervention of ferroptosis-related cardiomyopathy." (PMID 40695797, 2025). "In addition, endothelial SIRT1 deficiency impairs angiogenesis, causing inflammation and platelet hyperactivation to exacerbate CMD and cardiomyopathy, while upregulation of SIRT1 ameliorates low myocardial capillary density and fibrosis." (PMID 39598406, 2024). "Indeed, in AC5 overexpression models, prolonged catecholamine stress results in SIRT1 and FoxO3a inhibition that in turn decrease MnSOD transcription resulting in severe cardiomyopathy." (PMID 33671541, 2021). "Conversely, AC5 disruption protects the heart from the cardiomyopathy induced by chronic pressure overload and catecholamine stress, and leads to better exercise performance, most likely due to preserved SIRT1 and FoxO3 activity and MnSOD levels." (PMID 33671541, 2021). "CONCLUSIONS: Altogether our results suggest that horsetail extract might have potential in ameliorating manifested cardiomyopathy acting on SIRT1." (PMID 32486051, 2020). "Since heart failure due to cardiomyopathy is currently the leading cause of death in patients with DMD, SIRT1 activation might provide a prognostic advantage in patients with muscular dystrophies." (PMID 27073590, 2016). "Therefore, we performed animal experiments and cellular studies to examine whether apigenin confers protection against Dox-related cardiomyopathy through regulating the Sirt1/Atf5 pathway to influence the UPRmt." (PMID 37928261, 2023). "Additionally, it has been demonstrated that Sirt-1 can improve diabetes-related cardiomyopathy by activating AMPK and PGC1-a, which may also be influenced by the activation of the vitamin D receptor." (PMID 37764807, 2023). "Thus, this review aims to present a summary of the rapidly growing field of epigenetic regulatory mechanisms, as well as the epigenetic influence of SIRT1 on the development and progression of diabetic complications, including cardiomyopathy, nephropathy, and retinopathy." (PMID 33537003, 2020).
cardiomyopathy (continued). "Low to moderate (2.5- to 7.5-fold) cardiac-specific Sirt1 overexpression in transgenic mice has been demonstrated to protect cardiomyocytes from apoptosis and age-dependent degeneration, whereas its greater increase (12.5-fold) has a detrimental effect on these cells, leading to cardiomyopathy." (PMID 30513672, 2018). "A study on cardiac-specific SIRT1 knockout mice demonstrated that SIRT1 could promote the expression of mitochondrion-related genes, such as nuclear respiratory factor 2 (Nrf2) and mitochondrial transcription factor A (Tfam), to enhance cardiomyopathy via PGC-1α deacetylation." (PMID 40430054, 2025). "Among the sirtuin family members, SIRT1, SIRT3 and SIRT6 have attracted much attention as the potential cardioprotective modulators against inflammation, vascular remodelling, cardiomyopathy and the development of atherosclerotic plaques." (PMID 38894630, 2024). "This study examined the cardiac anti-cardiomyopathy (DC) protective effect of urolithin A in streptozotocin (STZ)-treated rats and investigated if this protection involves activation of SIRT1 signaling." (PMID 35241966, 2022). "Under DCM conditions, the activation of energy deprivation sensors, sirtuin-1 (SIRT1) and phosphorylation of AMPK can promote the removal of dysfunctional mitochondria and peroxisomes to reverse the development of cardiomyopathy." (PMID 35360240, 2022). "In addition, the myocardial antioxidation proteins (Nrf2, HO‐1, SOD1, SOD2), Sirt1 (a regulator of cellular ageing, apoptosis, stress, etc) and pAMPK (a regulator of cellular energy homeostasis) were down‐regulated in mouse hearts with doxorubicin cardiomyopathy." (PMID 32918384, 2020). "For example, SIRT1 activation has been shown to improve heart function, reduce cardiac fibrosis, and inhibit TGF-β/Smad3 in doxorubicin-induced cardiomyopathy in rats." (PMID 30050588, 2018). "Specifically, high doses of SIRT1 induced cardiomyopathy, whereas mild to moderate levels of SIRT1 expression did not exhibit this adverse effect." (PMID 38494853, 2024). "Though cardiomyopathy did not affect Sirt1 expression, a significant upregulation of total AMPK was found in both older and younger male patients." (PMID 37365150, 2023). "We showed that NOS3, CAV1 and SIRT1 are expressed in the cardiomyopathies as well as other non-cancer and non-heart related diseases." (PMID 36385157, 2022). "Previous study has shown that RES activates SIRT1 to inhibit ROS generation in cardiomyocytes, and also the activation of SIRT1 can improve cardiac function by blocking the development of cardiac fibrosis in a model of DOX-induced cardiomyopathy." (PMID 36235670, 2022). "In contrast, metformin and SGLT2 inhibitors activate SIRT1 and/or AMPK and promote autophagic flux to varying degrees in cardiomyocytes, which may explain their benefits in experimental cardiomyopathy." (PMID 32404204, 2020). "Signaling pathways such as SIRT1/NF-κB, SIRT1/p38 MAPK, SIRT1/TGF-β, SIRT1/AMPK may play an important role in maintaining the functioning of cardiomyocytes, influencing the functioning of ID structures during the cardiomyopathy development." (PMID 36408244, 2022). "However, none of the studies have investigated the role of SIRT1/Nrf2 in DOX-induced ferroptosis in cardiomyopathy." (PMID 35273493, 2021). "Interestingly, non-physiological overexpression of SIRT1 (20 fold) in cardiomyocytes leading to oxidative stress and apoptosis, while controlled overexpression of SIRT1 is able to delay cardiomyopathies due to advanced age." (PMID 29415476, 2018).
leukemia (54 papers, 2005 to 2025). A malignant (clonal) hematologic disorder, involving hematopoietic stem cells and characterized by the presence of primitive or atypical myeloid or lymphoid cells in the bone marrow and the blood. "In direct contrast, in leukemia, loss of H3K79me upon DOT1Li reduced H3K9ac and promoted H3K9me2 at target genic loci via a complex containing the deacetylase SIRT1 and H3K9 methyltransferase SUV39H1." (PMID 35733849, 2022). "Further, inhibition of Sirt1 causes the “fine-tuning” of circadian gene oscillation for some types of leukemia and in CML patient’s resulting in the complete recovery of BMAL1 oscillation." (PMID 30210557, 2017). "MYC is either amplified or shows misexpression in at least 50% of all cancers and a majority of human leukemia and lymphoma cases and SIRT1 is implicated in similar hematological malignancies." (PMID 28674522, 2017). "In turn, this condition predisposes leukemia cells to apoptotic cell demise when SIRT1 is inhibited." (PMID 21818379, 2011). "The role of SIRT1 was demonstrated in a study in CML mouse models and showed that when SIRT1 was deleted in these mice, it impaired the leukemia development, and TKIs were more effective in SIRT1-deleted mice." (PMID 40688985, 2025). "SIRT1 plays a critical role in promoting tumor cell survival and chemoresistance in various types of leukemia." (PMID 41471781, 2025). "Significant levels of SIRT1 and c-Myc expression have been identified in stem cells, including leukemia stem cells." (PMID 38397988, 2024). "In this review, we explore the role of SIRT1 in drug-resistant leukemia and its potential as a therapeutic target." (PMID 37833921, 2023). "SIRT1 is upregulated in leukemia stem/progenitor cells in CML and some AML, and plays pivotal roles in leukemogenesis, acquiring mutations and drug resistance." (PMID 35484199, 2022). "Ginsenoside Rg1 inhibits cell proliferation and induces cellular senescence in acute myeloid leukemia cells CD34+CD38- leukemia stem cells by activating Sirtuin 1 (SIRT1)/tuberous sclerosis complex 2 (TSC2) signaling pathway." (PMID 36171897, 2022). "In chemo-resistant stem-like cells from leukemia K562, EX-527 or SIRT1 knockdown increased the effect of Hsp90 inhibitors like 17-AAG and AUY922." (PMID 34650436, 2021). "In adult T cell leukemia/lymphoma, the SHP-1 protein has been shown to dephosphorylate and inactivate Sirtuin-1 (SIRT1) that repairs DNA of leukemia cells through homologous recombination." (PMID 34490276, 2021). "Taken together our findings suggest a link between Sirt1 and the oscillation of circadian genes in leukemia." (PMID 30210557, 2017). "Although a role for Sirt1 in regulating the circadian clock in leukemia has yet to be established, a role for Sirt1 in cancer has previously been demonstrated." (PMID 30210557, 2017). "To assess the expression status of SIRT1 in leukemia, we determined the mRNA levels of SIRT1 in mononuclear cells (MNCs) from 25 leukemic patients and 15 non-leukemic patients by real-time PCR." (PMID 26646449, 2016). "We next determined the mRNA and protein levels of SIRT1 in several leukemia cell lines by real-time PCR and Western blot analysis, respectively." (PMID 26646449, 2016). "A mouse leukemia model was established by transplanting lentivirus-infected K562 cells containing SIRT1 shRNA into sublethally irradiated NOD/SCID mice, and tumorigenesis was evaluated by detecting tumor weights and mice survival." (PMID 26646449, 2016).
leukemia (continued). "These striking results added a new dimension for the development of SIRT1 inhibitors for leukaemia therapy." (PMID 26091232, 2015). "To this end, we determined SIRT1 levels by quantitative PCR (QPCR) in the primary leukemia samples and in the leukemia cell lines used and compared these to SIRT1 expression in healthy PBMCs." (PMID 21818379, 2011). "Although with some variability among samples, SIRT1 expression in primary leukemia cells (B-CLL and AML) was found to be similar to that observed in healthy leukocytes." (PMID 21818379, 2011). "SPHK/S1P signaling upregulates SIRT1 expression in leukemia cells." (PMID 40470379, 2025). "Moreover, the SIRT family protein SIRT1 is also a crucial antiapoptotic molecule in certain leukemia cells, indicating potential interactions between different SIRT proteins in regulating apoptosis." (PMID 40317067, 2025). "Expression of SIRT1 in leukemia cell lines correlates with the degree of FAO." (PMID 37256177, 2023). "Moreover, SIRT1 drives lymphomagenesis and maintains leukemia stem cell potential by modulating lipid metabolism." (PMID 37256177, 2023). "In addition, SIRT1 is activated by the c-MYC oncogenic network in human FLT3-ITD+ AML leukemia stem cells (LSCs), which contributes to their maintenance and drug resistance." (PMID 35656547, 2022). "In addition to pluripotent components, epigenetic remodelers such as sirtuin-1 (SIRT-1) play vital roles in maintaining leukemia stem cell properties, and they are always triggered during hypoxic conditions." (PMID 35847841, 2022). "Many of the treatment failure–associated cytokines (e.g., SIRT1 and CXCL1) could support leukemia stem cell proliferation and survival." (PMID 36047494, 2022). "Sirt1 expression in leukemia cell lines was first determined." (PMID 36058936, 2022). "For example, downregulation of SIRT1 expression by EX527 enhanced cell sensitivity to bortezomib in multiple melanoma, while SIRT1 inhibition by tenovin-6 in combination with tyrosine kinase inhibitor imatinib targeted leukemia stem cells, leading to reduction of their growth." (PMID 34445277, 2021). "Taking together, our data suggests that inhibition of Sirt1 is a feasible approach to modulating circadian gene activity in leukemic patients as part of a chronotherapy-based approach to treatment of acute forms of leukemia." (PMID 30210557, 2017). "We used a pharmacological-based approach to see whether Sirt1 played a role in regulating the circadian clock circuitry in both acute and chronic forms of leukemia." (PMID 30210557, 2017). "We wanted to see whether interfering with Sirt1 activity alters the oscillation of circadian genes in leukemia." (PMID 30210557, 2017). "K562 cells demonstrated relatively higher levels of SIRT1 mRNA than other leukemia cell lines." (PMID 26646449, 2016). "Our study suggests that SIRT1 deacetylase enhances NHEJ DNA damage repair efficiency in myeloid leukemia cells, and that targeting SIRT1 may provide a novel strategy for improving leukemia treatment and for overcoming DNA damage based chemotherapy resistance." (PMID 26646449, 2016). "Similarly, relatively higher levels of SIRT1 proteins were observed in K562 cells, compared to other leukemia cell lines." (PMID 26646449, 2016). "Recently, the histone deacetylase sirtuin 1 (SIRT1) has been shown to be important in leukemia." (PMID 25884180, 2015).
leukemia (continued). "Moreover, increased SIRT1 levels were detected in chemoresistant leukemia cells and in imatinib-resistant chronic myelogenous leukemia cells." (PMID 21818379, 2011). "However, as we show here with SIRT1 and leukemia, there are still many pieces to be discovered." (PMID 37833921, 2023). "We first examined whether SIRT1 was increased in primary leukemia cells from patients with ALL." (PMID 25884180, 2015). "Thus, methods to block the function of SIRT1 may be useful for the development of ideal therapeutic agents for leukaemia, especially in patients with ATL." (PMID 26091232, 2015). "SIRT1 mediates the restructuring of lipid metabolism and elevates FAO levels in chemoresistant leukemia cells." (PMID 37256177, 2023). "Similarly, the participation of SIRT1 in the maintenance of leukemogenesis and in the acquisition of chemoresistance could be used as a therapeutic target, although little has been explored in this regard in leukemia." (PMID 37833921, 2023). "To further corroborate the roles of SIRT1 in human leukemia, we carried out CRISPR (clustered regularly interspaced short palindromic repeats) gene editing to knockout SIRT1 in human primary B/M MPAL and B-ALL cells." (PMID 35484199, 2022). "The effect of MC2494 derivatives on SIRT1 and SIRT2 protein expression was then investigated in leukemia U937 cells by Western blot." (PMID 31726691, 2019). "Firstly, by treating leukemia U937 cells with the analogs and comparing their biological activity to that induced by MC2494, we detected a decrease in the expression level of SIRT1 and SIRT2." (PMID 31726691, 2019). "In terms of downstream targets, in leukaemia, it has been shown that BCL11A abrogates p21 transcription possibly via direct regulation of SIRT1 (refs 41, 42)." (PMID 25574598, 2015). "Alternatively H3K79me2 was suggested to oppose H3K27me3 and H3K9me3 via SIRT1/SUV39H1 in leukemia." (PMID 35733849, 2022). "The suppression of metabolic activation and protein synthesis pathways by Sirt1 knockout may thus improve aging HSC functions and inhibit their transformation into leukemia stem cells for MPAL development down the road." (PMID 35484199, 2022). "In the present study, we demonstrated that SIRT1 is upregulated in T-ALL and could promote proliferation of T-ALL cells and plays an important role in promoting leukemia development in T-ALL by targeting p27 for ubiquitin-mediated proteasomal degradation." (PMID 34407842, 2021). "Additionally, we screened their effect on the enzymatic activity of the histone deacetylase sirtuin family (SIRT1, SIRT2, SIRT3, SIRT5 and SIRT6) using both recombinant enzymes and nuclear lysates from leukemia cells." (PMID 32587297, 2020). "Moreover, combination of Sirt1 inhibitor, Ex527, with an HDAC inhibitor, valproic acid, or butyrate, induced apoptosis in human leukemia cells." (PMID 32698385, 2020). "In leukemia cells, HDAC inhibitors were found to induce upregulation of Bax, a pro-apoptotic Bcl2 family-member whose translocation to mitochondria is normally prevented by SIRT1." (PMID 21818379, 2011). "In the case of resveratrol, this includes SIRT1 activation,inhibition of cyclooxygenase and NFκB, induction of antioxidant enzymes,and activation of AMPK in vivo, in addition to the inhibitionof the leukemia-related kinases and S6K1 reported here." (PMID 20157535, 2009). "Knocking out SIRT1 did not change the CD4+ CD8+ phenotype of leukemia cells." (PMID 34407842, 2021).
leukemia (continued). "To confirm the role of SIRT1 inhibition in the synergy between sirtuin and HDAC inhibitors in leukemia cells we silenced this sirtuin member in Jurkat cells by transfecting the cells in the presence of a SIRT1-specific siRNA or a non-targeting siRNA as a control." (PMID 21818379, 2011).